STAT3 (signal transducer and activator of transcription 3)
Diseases named in the same sentence as STAT3 in open-access papers (continued):
Sharing a sentence is not in itself a finding about the gene and the disease.
tumor (continued). "Previous studies showed that axitinib, an alternative VEGFR inhibitor, had the potential to modulate antitumor immunity by suppressing STAT3 expression and reversing MDSCs mediated tumor-induced immunosuppression." (PMID 27926489, 2017). "Our findings suggested that the tumor suppressive effect of GMI was via inhibition of IL-6/Stat3 signaling." (PMID 29050290, 2017). "In transgenic mice model, STAT3 also establishes an inmuunosuppressive microenvironment during the early stages of breast carcinogenesis to promote tumor develop and metastasis." (PMID 28422733, 2017). "It is likely that BTICs depend more on STAT3 for their cell cycle progression, while STAT3 contributes equally to migration and proliferation in differentiated tumor cells." (PMID 28030813, 2017). "Independent shRNA-mediated HIF-1α knockdown also decreased wound healing, cell migration, invasion, and tumor formation, showing that the STAT3/HIF-1 α signaling pathway is responsible for tumorigenesis in MPNST." (PMID 28825044, 2017). "The expression of STAT3 was higher in metastasis lymph node lesions than ICC primary tumor tissues in most cases (9/15), which suggested that high expression of STAT3 correlated with a greater likelihood of lymph node metastasis." (PMID 28032598, 2017). "During radiation, induced Notch2 accelerates tumor malignancy by increasing mesenchymal markers through IL6/JAK/STAT3 signaling axis." (PMID 28445439, 2017). "Through its major downstream target STAT3 several tumor promoting pathways are activated, including HIF1-α and VEGF." (PMID 28859644, 2017). "Morphometric analysis showed an increased expression of Stat3 and pStat3 in the tumor brain tissues compared with control tissues." (PMID 28415725, 2017). "These all activate Stat3/NF-κB in both stromal and tumor cells, creating a positive feedback loop to maintain a chronic inflammatory state in tumor cells." (PMID 28209166, 2017). "Recently, numerous reports have shown that aberrant and persistent activation of the STAT3 signaling pathway contributes to tumor progression." (PMID 29207645, 2017). "Consistent with in vitro results, DCZ3301 inhibited tumor growth in vivo with decreased phospho-STAT3." (PMID 29022919, 2017). "As nobiletin inhibited general tumor angiogenesis in vitro by mediating Src/FAK/STAT3 signaling, in vivo experimentation is very important to confirm this signaling pathway." (PMID 28468300, 2017). "We mostly observed an increased STAT3 expression in tumor samples compared to healthy counterparts except for liver and lung." (PMID 28801664, 2017). "Here, we found that curcumin combination with EGCG attenuated the tumor CM-induced transition of NECs toward TECs by inhibiting JAK/STAT3 signaling pathway." (PMID 28967875, 2017). "STAT3 is a transcription factor involved in cytokine and receptor kinase signal transduction and its activation in tumor cells promotes metastasis and resistance to chemotherapy." (PMID 28750090, 2017). "In the same model, S-adenosylmethionine (SAMe) and methylthioadenosine (MTA) inhibited IL-6/STAT3 and lowered tumor burden." (PMID 29108270, 2017). "Increasing evidence from functional studies indicates that GP130-mediated IL-6/STAT3 signaling activation contributes to tumor invasion and angiogenesis which are essential for tumor metastasis." (PMID 28672024, 2017). "In the NSCLC study, the miR-197/CKS1B/STAT3-induced PD-L1 network leads to tumor progression, and miR-197 is an inverse indicator of PD-L1 expression and predicts shorter OS." (PMID 29029502, 2017). "STAT3 is a constitutive activator in tumor cells and is involved in the initiation and progression of epithelial ovarian carcinoma." (PMID 28970834, 2017). "Although many studies have demonstrated the positive role of STAT3 in promoting tumor angiogenesis, further research is needed to illuminate the detailed mechanisms of STAT3 in this process." (PMID 28978186, 2017).
tumor (continued). "In situ examination of tumor tissues confirmed varied presence of the STAT3 and pSTAT3 in oral tissues." (PMID 28155253, 2017). "PL2L60 can promote tumor cell survival and proliferation in vitro through up-regulation of STAT3 and BCL2 genes." (PMID 28545024, 2017). "Taken together, our data reveal that IL-8 secreted by tumor cells activates JAK/STAT3 signaling pathway and induces the production of IL-8 in NECs, and this amplification loop promotes the transition of NECs toward TECs." (PMID 28967875, 2017). "With our ability to reconstitute the tumor tissue from the tumor cells and immune cells, we reasoned that our method can directly study lymphocytic trafficking mediated by tumor intrinsic STAT3 signaling in vivo." (PMID 28008146, 2017). "In turn, activated STAT3 is capable of stimulating pro-oncogenic pathways in cell survival, apoptosis, invasion, and tumor immunosurveillance." (PMID 28350325, 2017). "The activation and crosstalk between STAT3 and NF-κB is commonly outcome of chronic inflammation and tumour microenvironments, especially with inflammatory cells that infiltrate tumours." (PMID 28383063, 2017). "Cross talk with other molecular pathways contributes to STAT3 regulation in cancer, and STAT3 is also aberrantly activated by the oversupply of growth factors from the tumor microenvironment." (PMID 28626726, 2017). "In conclusion, we have developed an all-nanocrystal biosensing system for the effective detection of a tumour-specific growth factor STAT3 DNA." (PMID 28661466, 2017). "To validate the signalling pathway alterations in tumour-induced immature DCs, we selected NF-κB and STAT3 from the high impact signalling pathways for further verification." (PMID 28350008, 2017). "Accumulating evidence implicates the important role of JAK2/STAT3 in tumor and macrophage polarization." (PMID 28630636, 2017). "Herein, we developed biostable iDR-NC/neoantigen complexes as nanovaccines that incorporated CpG and Stat3 shRNA, as well as tumor-specific neoantigens for efficient co-delivery and immunomodulation in cancer immunotherapy." (PMID 29133898, 2017). "To investigate human tumor intrinsic factors that can potentially regulate the immune cells in our system, we silenced STAT3 signaling in the tumor compartment." (PMID 28008146, 2017). "Interphase FISH analysis and the FICTION technique on the FFPE tumor samples, and Stat3 gene sequencing on genomic DNA, were carried out." (PMID 28415725, 2017). "The bisulfite treatment of tumor DNA and methylation-specific polymerase chain reaction (MS-PCR) method was used to determine the STAT3 gene promoter methylation." (PMID 28709401, 2017). "In contrast to the transient activation of STAT3 in normal cells, many tumours exhibit constitutive STAT3 activity." (PMID 28186993, 2017). "Our studies demonstrate that HDAC7 functions as a tumor promoting factor by deacetylating STAT3, therefore reducing STAT3 activation." (PMID 29126425, 2017). "Activated Stat3 promotes tumor cell proliferation and survival, immune suppression, invasion, and angiogenesis." (PMID 28415725, 2017). "With the aim of elucidating the relationship between Stat3 expression and tumor vessels abnormalities in the PCNLs, in this study we evaluated Stat3 and pStat3 expression by Real-time PCR and by immunohistochemistry in biopsy sections from PCNSL patients." (PMID 28415725, 2017). "All together, these findings support the notion that the CDK5/p35/STAT3 pathway mediates the tumor-suppressive function of miR-26a, and that p35 deregulation through miR-26a plays an important role in tumor growth." (PMID 28640256, 2017). "In particular, CD24 has been shown to enhance the activation of signal transducer and activator of transcription 3 (STAT3) in different tumor types." (PMID 28320418, 2017).
tumor (continued). "Further studies are required to determine the molecular mechanisms by which the STAT3-blocked HCC vaccine promotes the crosstalk between STAT3 in tumor cells and immune cells, and relevant techniques before its use in clinical trials." (PMID 29115974, 2017). "It is suggested that suppression of TGF-β signaling promotes tumor growth in an IL-6/STAT3-dependent way." (PMID 28852270, 2017). "Nitric oxide can activate protein kinase B (AKT) and signal transducer and activator of transcription 3 (STAT3), which play key roles in multiple cellular processes including tumor glucose metabolism." (PMID 28380434, 2017). "The miR-9 is secreted by tumor cells, and activates STAT3 in ECs by inhibiting SOCS5 levels, leading to migration of ECs and tumor angiogenesis." (PMID 28978186, 2017). "Knockdown of Stat3 significantly reduced the malignant transformation and tumor proliferation, and induced cell damage in vitro and in vivo." (PMID 29133922, 2017). "When we quantitated the TILs using human CD45-fluorophore conjugate in IHC, STAT3 suppressed tumor cells showed increased tumor infiltrating human CD45 cells." (PMID 28008146, 2017). "Signal transducer and activator of transcription 3 (STAT3) is an oncogene that takes part in tumor progression and metastasis." (PMID 28468300, 2017). "When we specifically tested the migratory behavior of CD8+ T-cells from HNSCC cancer patients, we noted that STAT3 signaling in tumor cells can suppress lymphocytic migration in vitro." (PMID 28008146, 2017). "Previous studies demonstrated Stat3 siRNA or kinase inhibitors reduced tumor proliferation in vitro." (PMID 28069035, 2017). "To reveal the mechanism underlying the role of FAK in tumor migration/metastasis, we examined the effect of FAK knockdown on the levels of Src, p-SrcY416, ERK1/2, p-ERK1/2, Stat3, p-Stat3Y705 and E-cadherin by western blotting." (PMID 28108732, 2017). "Using our autologous model, we were able to genetically modify STAT3 signaling in the tumor compartment and demonstrate its ability to regulate the tumor infiltrating human lymphocytes that can promote the tumor growth rate." (PMID 28008146, 2017). "It has been shown that STAT3 activation enhances invasion and motility of tumor cells, contributing to the aggressiveness of the tumor." (PMID 29245982, 2017). "As a member of the IL–10 cytokine family, IL-22 is a potent activator of STAT3, having an important role in tumorigenesis and tumor development." (PMID 28445985, 2017). "Reg3g produces these effects by activating the JAK2/STAT3 signaling pathway in DCs, triggering the generation of an immunosuppressive tumor microenvironment." (PMID 28880262, 2017). "We now show that the ShcA phosphotyrosine motifs potentiate immune suppression by limiting signal transducer and activator of transcription (STAT)-1-driven anti-tumour immunity, while simultaneously increasing STAT3 immunosuppressive signals." (PMID 28276425, 2017). "IL11Rα blocking Ab reduced STAT3 phosphorylation and combination treatment with doxorubicin resulted in a significant reduction in tumour growth (p < 0.05) compared to Ab, doxorubicin, or IgG control." (PMID 28186993, 2017). "Stat3 immunohistochemical expression showed high levels of total and phosphorylated Stat3 protein in tumor brain compared to normal brain." (PMID 28415725, 2017). "Data obtained showed different STAT3 PTMs profiles among the analyzed tumor grades which correlate with differences in the amount and distribution of specific STAT3 interactors as well as the expression of STAT3 target genes." (PMID 28489571, 2017). "Niclosamide has also recently been reported as a potent STAT3 inhibitor that functions as a tumor suppressor in cancer cells." (PMID 28877265, 2017). "Numerous studies show that IL-6/STAT3 signaling pathway plays an important role in tumor metastasis." (PMID 29100297, 2017). "Stat3 is required for tumor cell proliferation, infiltration, differentiation and apoptosis inhibition." (PMID 28069035, 2017).
tumor (continued). "Further investigation must be conducted to unravel the role of STAT3 in actual metastasis of TNBC tumor cells to a secondary site." (PMID 28030809, 2017). "As mTORC2 was reported to phosphorylate Akt-pS47329, 30, we examined the status of Akt, as well as ERK and STAT3, two critical pathways in regulation of tumor cell growth and invasion." (PMID 28176801, 2017). "STAT3’s functions and its critical roles in tumorigenesis and tumor maintenance have qualified it as a valid target for the development of novel anticancer therapeutic modalities." (PMID 28720093, 2017). "Mithocondrial STAT3 interacts with respiratory complexes I, II, and V of the electron transport chain and influences ROS production, thus promoting tumor cell survival and invasion." (PMID 28489571, 2017). "The results showed a constitutively activated STAT3 (pY705-STAT3) in all tumor grades compared to the matched normal sections." (PMID 28489571, 2017). "Accumulating evidence has demonstrated that the tumor suppressor functions of Smads are compromised by oncogene products, such as c-Ski, Bcl6, c-Myc, Evi-1 and STAT3, through direct Smad–oncoprotein interactions during carcinogenesis." (PMID 28455959, 2017). "Astaxanthin blocks STAT3 activity by forming hydrogen bond with Met 1428, Glu 1523, Arg 1593, and Asn 538 on STAT3 in tumor cells, abrogating cell proliferation, invasion, and angiogenesis." (PMID 28978186, 2017). "Based on the representation of each class (AP‐1/NF‐κB/STAT3) of transcription factors, individual tumor tissues were segregated in different categories and their distribution was evaluated by paired t‐test." (PMID 28155253, 2017). "STAT3 usually acts as a tumor promoter, although its role as a tumor suppressor has been recently reported." (PMID 28864784, 2017). "MiR-146b shows tumor suppressive function through the regulation of NF-κB-IL-6/STAT3 signaling pathway in breast cancer." (PMID 29162923, 2017). "QRHX treatment blocked the response of macrophages to tumor signals by suppressing CXCL12/CXCR4/JAK2/STAT3 expression and induced a remarkable decrease of the recruitment of M2 macrophages, suggesting the attenuation of M2 subtype cells function by QRHX." (PMID 28630636, 2017). "Researches showed that inflammatory mediators, such as interleukin 6 (IL-6), Toll-like receptor (TLR), signal transducer and activator of transcription 3 (STAT3), and nuclear factor-κB (NF-κB), are critical in the transformation from inflammation to tumor." (PMID 29190960, 2017). "We next injected these cells into the mammary fat pads of CD8+/+ or CD8−/− mice, to examine the functional significance of STAT1 and STAT3 in modulating the balance between pro- versus anti-tumour immunity." (PMID 28276425, 2017). "In summary, we demonstrated that overexpression of miR-223-3p in the human head and neck cell line resulted in decreased expression of STAT3 but also in decreased formation of neo-vessels in an orthotopic xenograft tumor model." (PMID 28915663, 2017). "Previously, we proved that abrogation or inhibition of STAT3 attenuated tumor growth in vitro and in vivo." (PMID 29115974, 2017). "Collected the tumor tissues were subjected to western blot showed decreased protein expression of pSTAT3 ser727, total STAT3, Bcl-2, Bcl-XL, FAS, cyclin D2, MMP2, and MMP9 in metformin treated vs. control mice." (PMID 28114390, 2017). "STAT3-blocked whole HCC cell lysates inhibited tumor growth and tumorigenesis, and prolonged the survival of tumor-bearing mice." (PMID 29115974, 2017). "We determined that SFN exhibits a strong anti-tumor effect against GBM cells via ROS-mediated inactivation of STAT3 signaling." (PMID 28054986, 2017). "For R2016-treated tumor cells, a dose-dependent reduction of phosphorylated-STAT3 was observed in both LLC and B16F10 cells." (PMID 28282460, 2017). "PI3K/AKT/mTOR and JAK/STAT3 pathways play a vital role in tumor cell proliferation, and the inhibition of theses pathways contributes to apoptosis in tumor cells." (PMID 27564113, 2017).
tumor (continued). "The inhibition of STAT3 phosphorylation by oleanolic and corosolic acids, two naturally occurring triterpenes, suppressed tumor-mediated M2 polarization and IL-10 production by macrophages." (PMID 28197019, 2017). "An immunohistochemistry assay revealed an increase in the mean positive areas for cleaved caspase‐3 and phosph‐JNK and decrease in phospho‐STAT3 in alternol‐treated tumour tissues." (PMID 27624867, 2017). "STAT3 is frequently abnormally activated in various tumors and its constitutive activation directly contributes to tumor development and progression." (PMID 28054986, 2017). "Correlations of the expression levels with the presence of aberrant vessels were analyzed by confocal laser microscopy analysis, using FVIII as endothelial cell marker, CD133 and nestin as CSC marker, CD20 as tumor cell marker, and Stat3." (PMID 28415725, 2017). "Blocking of constitutive STAT3 signaling results in growth inhibition and apoptosis of STAT3-positive tumor cells in vitro and in vivo." (PMID 29312162, 2017). "In vivo, metformin treatment led to a decrease in tumor weight as well as reductions of STAT3, pSTAT3 ser727, its target proteins." (PMID 28114390, 2017). "We euthanized the tumor-bearing mice, collected the tumors, extracted the proteins, and found that Atn downregulated the STAT3 phosphorylation." (PMID 27861147, 2017). "The trimeric interaction of IL-6 with soluble IL-6R and the common gp130 subunit is known to activate STAT3 and promote tumor growth." (PMID 29207662, 2017). "The results indicated that the blockade of the STAT3 pathway by CuB synergistically increased anti-tumor activity of Adriamycin." (PMID 27418139, 2017). "Previous study showed that upregulated MMP-2/9 contribute to cells migration and invasion abilities through STAT3-dependent signaling pathway in tumor cells." (PMID 29383152, 2017). "In GBM for example, STAT3 has been well documented as a facilitator of tumor cell proliferation, invasion, and angiogenesis." (PMID 28100038, 2017). "Anti-tumor effects of Stat3 knockdown has been demonstrated by means of small interfering RNA (siRNA), micro-RNA (mi-RNA), or small molecule inhibitors." (PMID 28415725, 2017). "To further support our in vitro result, we inoculated athymic nude mice with MFs and cancer cells, and found that suppression of TGF-β and JAK2/STAT3 signaling by inhibitors reduced tumor size and minimized tumor histopathology in vivo." (PMID 28819126, 2017). "It is well known that STAT3 and its downstream genes not only promote cancer growth, survival, angiogenesis and metastasis, but also interfere with cellular apoptosis and anti-tumor immune responses." (PMID 29152078, 2017). "Studies have demonstrated that STAT3 is aberrantly activated in a number of human cancers and plays a crucial role in tumor initiation and progression by regulating Bcl2 family members." (PMID 29254150, 2017). "When we compared the histology between the STAT3 silenced and control tumors, we noted increased tumor necrosis in the STAT3 silenced tissues." (PMID 28008146, 2017). "Inhibition of sorcin expression can down- regulate the expression of CTSZ, MMP2, MMP9 and p-STAT3 followed by suppression of tumor growth and metastasis." (PMID 29262638, 2017). "This circuit can also be triggered by other extrinsic signals from the tumor microenvironment or intrinsic cancer cell signals (such as oncogene activation and tumor suppressor inactivation), which activate IL-6R or STAT3." (PMID 28388577, 2017). "Together these results for the first time demonstrated the anti-tumor effects of STAT3 inhibitor S3I-201 in HPV-negative ASCC mouse model and its multiple effects on cancer cells and immune system." (PMID 28747781, 2017). "Accumulating evidence has shown that of the inhibition of STAT3 activity in cancer cells can inhibit tumor growth and enhance chemotherapy sensitivity in HCC cells." (PMID 26061710, 2017).